INS (insulin)
Diseases named in the same sentence as INS in open-access papers (continued):
Sharing a sentence is not in itself a finding about the gene and the disease.
diabetes (continued). "An animal experiment revealed that reduced brain insulin signaling in mouse models of diabetes increased tau beta phosphorylation and amyloid beta peptide levels, both of which are associated with WMHs and cognitive decline." (PMID 33282807, 2020). "Sensitivity analyses were also performed by repeating the models with the participants who were taking diabetes medication (insulin and/or oral hypoglycemic) in wave 6 (n = 45) excluded." (PMID 31456532, 2020). "In diabetes, β cell mass and function are diminished, leading to insufficient insulin secretion and hyperglycemia." (PMID 32133389, 2020). "In this study, a quarter of patients with type 2 diabetes mellitus who initiated basal insulin (BI) therapy due to uncontrolled hyperglycaemia by OADs discontinued BI therapy within 6‐month follow‐up." (PMID 32318640, 2020). "Despite the lack of clear neurophysiological markers, there is a strong epidemiologic bond between diabetes and the development of dementia, possibly related to glycemic control and insulin dysregulation." (PMID 33120406, 2020). "In diabetes, β cells are either destroyed by the immune system (type 1 diabetes) or unable to secrete sufficient insulin in response to stimulation (type 2 diabetes)." (PMID 33178692, 2020). "The role of insulin in diabetes mellitus has transformed dramatically from the glucocentric approach to an outcome-measures-focused approach." (PMID 32308680, 2020). "Compared to the non-T2D control group, a higher percentage of participants in the incident T2D case group had a family history of diabetes (p = 0.018) and had been treated with insulin or oral medications during pregnancy (p < 0.001)." (PMID 32433647, 2020). "Their physiology is a topic of intensive studies aiming to understand the biology of insulin production and its role in diabetes pathology." (PMID 32003782, 2020). "Since these patients are generally managed with supplemental insulin, Type 1 Diabetes can also be called Insulin-Dependent Diabetes Mellitus (IDDM)." (PMID 33227918, 2020). "The term “diabetes mellitus” defines a group of metabolic diseases characterized by hyperglycemia resulting from a defect in insulin secretion and/or action." (PMID 33114431, 2020). "These parameters, as well as the basal insulin dose, are established by an expert (e.g., diabetologist or certified diabetes educator), to achieve the best fit for a patient’s insulin requirements." (PMID 32664432, 2020). "Effective aerosol delivery to the pulmonary system gives expansive and novel applications to aerosol therapy, such as inhaled insulin to treat diabetes." (PMID 32785196, 2020). "In subgroup analyses, strongest effects were detected among patients who used only other diabetes medications than insulin or metformin in 2016 (3.56 mmol/mol, 95% CI 2.50–4.62)." (PMID 33246453, 2020). "The affective management of diabetes, therefore, is to prevent excess postprandial increases in the blood glucose level and improve insulin resistance." (PMID 33255297, 2020). "This study showed that in overweight and obese adults with pre-diabetes the daily time use composition of sleep, ST, LIPA and MVPA was significantly associated with BMI, body fat %, WC, triglycerides, insulin, HOMA-IR and hs-CRP." (PMID 32131847, 2020). "Nonetheless, the finding of increased markers (2-hydroxybutyrate and aminoadipate) in RTT subjects and evidence of insulin resistance in animal models warrants additional clinical monitoring of diabetes in RTT." (PMID 32161522, 2020). "This study aimed to assess the outcomes of adding basal insulin compared with thiazolidinediones (TZDs) or dipeptidyl peptidase-4 inhibitors (DPP-4is) as a third antidiabetic agent in patients with type 2 diabetes mellitus (T2DM)." (PMID 32238842, 2020). "From the patient’s personal history: central obesity, arterial hypertension, treated with olmesartan medoxomil, diabetes mellitus 2, treated with repaglinide and glargine insulin, and cardioaspirin for prevention." (PMID 33336031, 2020).
diabetes (continued). "It is unclear why these secondary symptoms would be reported without reporting changes in standard measures for presence of diabetes, such as insulin levels, fasting glucose, and HbA1c." (PMID 32341338, 2020). "To date, substantial studies have been focused on differentiating insulin-secreting β-cells for the realization of stem cell-derived β-cell transplantation to cure diabetes." (PMID 32824212, 2020). "Insulin resistance, that is, an impaired cellular response to insulin stimulation, is the main characteristic of type 2 diabetes and contributes to downstream diabetes-related cellular and organ damage." (PMID 33344443, 2020). "Diabetes health education should focus on how to prevent diabetes and the contents of health education should be different for differernt age groups;on diabetes treatment, the use of insulin and oral hypoglycemic drugs education should be strengthened." (PMID 32576159, 2020). "Four had mild hypoglycaemia leading to a reduction in the insulin dose in the three patients with insulin‐treated diabetes." (PMID 32107855, 2020). "For example, β-cell specific knockout of the IR (βIRKO), global knockout of IRS1 or islet specific deletion of IRS2 (PIrs2KO) resulted in defective glucose-stimulated insulin secretion, and mice developed glucose intolerance and diabetes with age." (PMID 32150819, 2020). "In patients with diabetes mellitus, the number and functioning of pancreatic β-cells deteriorate over time, leading to an increase in insulin resistance and a reduction in insulin secretion." (PMID 32455131, 2020). "Hyperglycemia is the core feature of the type 1 diabetes mellitus (T1DM) and type 2 diabetes mellitus (T2DM), following insulin deficiency and impaired insulin secretion or sensitivity leads insulin resistance (IR), respectively." (PMID 32998300, 2020). "For example, flavonoids have been shown to increase insulin secretion and reduce insulin resistance, suggesting that these phytochemicals provide some benefits in obesity and diabetes." (PMID 32012681, 2020). "The diabetes drugs most frequently mentioned by consumers are insulin, metformin and Xiaoke pills, The most concerned complication is caidiovascular disease and diabetic eye disease." (PMID 32576159, 2020). "Associations of beta cell autoimmunity, as assessed by presence of GAD65 antibodies, with insulin requirement and diabetes complications have been investigated in prevalent adult-onset diabetes." (PMID 31713011, 2020). "The impact of the online CME program on physicians’ knowledge in the management of diabetes through lifestyle modification, use of OGLDs, and insulin therapy was evaluated." (PMID 33081765, 2020). "Another study, fully in line with our observations, has demonstrated that transgenic mice overexpressing miR-7a in pancreatic β cells developed diabetes mellitus due to impaired insulin release and β cell dedifferentiation." (PMID 32640511, 2020). "Studies have shown that RS can delay the increase of postprandial blood glucose, reduce body weight, promote insulin secretion and increase insulin sensitivity, playing an important role in preventing the occurrence and development of diabetes." (PMID 32168825, 2020). "The hormone released by PP cells inhibits insulin secretion in the body, and PP cell percentage and distribution increase significantly in the course of diabetes." (PMID 32121443, 2020). "One physician referred to closed‐loop as ‘the gold standard in terms of insulin management’ (2/AD/Phys/1), whereas others described it as ‘revolutionary’ (1/PA/Diet/9) and ‘the way forward’ for diabetes care (2/PR/Nurs/7)." (PMID 31943318, 2020). "The eGDR method has been widely used to evaluate, in a non-invasive way, the insulin sensitivity in patients with diabetes." (PMID 32267356, 2020).
diabetes (continued). "The phenotypes resemble permanent neonatal diabetes in the human and therefore serve as a widely used model for the studies of beta-cell dysfunction and a model for insulin supplementation and transplantation studies." (PMID 32699230, 2020). "Diabetes mellitus (DM) is considered as a metabolic disease that results in impaired glucose and insulin homeostasis." (PMID 32471242, 2020). "Fifty‐four percent of the diabetes patients received medication: oral glucose‐lowering drugs (80%), lifestyle therapy (55%), and insulin treatment (15%)." (PMID 32378803, 2020). "Type 2 diabetes mellitus (T2DM) accounts for 90-95% of all cases of diabetes and results from a progressive defect in insulin production and insensitive response of the body to insulin." (PMID 32858940, 2020). "Keynote of gold nanoparticle: diabetes mellitus, nursing, insulin, antidiabetic, drugs, and new system for drug delivery." (PMID 32880218, 2020). "Accordingly, diabetes patients, with low insulin secretion, experience hyperglucagonemia although their somatostatin secretion is even upregulated." (PMID 32774668, 2020). "Diabetes is a metabolic disease which induced either due to the inability of pancreas to secrete sufficient insulin in body or when body is unable to use insulin effectively for the regulation of blood sugar." (PMID 32148658, 2020). "The new SRS affected all community-dwelling Finnish T2D patients utilizing any other diabetes medication than insulin because in Finland, all community-dwelling residents are eligible for reimbursement for prescription medications." (PMID 33246453, 2020). "Diabetes mellitus (DM) is a widespread metabolic disorder disease, characterized by insulin resistance and a constant decrease in insulin secretion, and it is expected to rise to 592 million by 2035 that threatening human health." (PMID 32914833, 2020). "The insulin delivery via the AERx® insulin diabetes management system (iDMS) was studied in healthy smokers and non-smokers." (PMID 32850233, 2020). "Diabetes mellitus is a group of metabolic disorders characterized by hyperglycemia, which results from defects in either insulin secretion or insulin action, or both." (PMID 33200060, 2020). "Glucose and insulin plasma concentrations under fasting conditions in both healthy and type 2 diabetes mellitus (T2DM) subjects are expressed at characteristic concentrations for each individual’s nutritional status." (PMID 32283715, 2020). "Diabetes mellitus is a chronic endocrine disease in which an elevation of blood glucose level occurs as a result of reduced or inability of pancreas to produce insulin or due to peripheral tissue uptake defects of insulin." (PMID 33066443, 2020). "Abnormity of insulin sensitivity and β-cell function which thought to be the main physiopathologic mechanism exists many years before diabetes development." (PMID 32443387, 2020). "Previous studies had shed inconsistent light on the impact of insulin on the human myocard in diabetes." (PMID 32308680, 2020). "Regarding the potential for translation to the clinic, our results suggest that two salivary band areas, 1452 cm-1 and 836 cm-1, can be considered noninvasive spectral biomarkers of monitoring diabetes treated with insulin." (PMID 32182246, 2020). "A total of 11 focus groups and 1 interview were carried out; 6 focus groups were carried out with insulin pump users (n=19), and 5 focus groups and 1 interview were carried out with diabetes specialist HCPs (n=20)." (PMID 32356776, 2020). "This assessment is essential in planning postoperative diabetes management, especially if withdrawal of insulin is planned." (PMID 32743907, 2020). "Hypoglycemia is defined as a decrease in blood glucose levels below 70 mg/dL in patients with diabetes treated with insulin or oral hypoglycemic agents (OHAs)." (PMID 32774458, 2020). "Diabetes mellitus is a metabolic disease resulting from defects in insulin secretion, insulin action, or both." (PMID 33204733, 2020).
diabetes (continued). "Diabetes is characterized by high blood glucose levels due to the inability of pancreatic β cells to produce sufficient insulin to meet the needs of the body." (PMID 31941883, 2020). "Diabetes mellitus refers to metabolic diseases which are characterized by hyperglycemia that develops as a result of impairment in insulin secretion, insulin action, or both." (PMID 32983244, 2020). "Indeed, diabetes mellitus is a metabolic disorder characterized by chronic hyperglycemia with an excessively high blood sugar level corresponding to a fasting blood sugar level greater than 1.26 g/L (7 mmol/L) twice linked deficiency in either insulin secretion, insulin action, or both." (PMID 32724757, 2020). "Clinical expert and international diabetes organizations’ position statements support the management of good glycemia during acute physical exercise by adjusting exogenous insulin and/or carbohydrate intake." (PMID 33193089, 2020). "On follow-up, there was evidence of a honeymoon phase at 4 months after DKA onset in the patient with prior diabetes where the insulin requirement decreased from 0.87 to 0.51 units/kg/day, suggesting some endogenous insulin secretion by residual beta cells." (PMID 32733645, 2020). "Other studies of the effects of IL-6 receptor blockade on insulin sensitivity/resistance in patients with RA excluded patients with diabetes." (PMID 32907617, 2020). "Previous studies have also shown that insulin signal transduction pathway plays a crucial role in the pathogenesis of diabetes, which is of great significance for the study of insulin signal transduction in type 2 diabetes." (PMID 32265717, 2020). "Abundance of E2F3 contributed to insulin secreting β cell proliferation, providing promising alternative therapy for diabetes." (PMID 32348429, 2020). "Insulin dose per kg body weight was 0.7 (0.5–0.9) IU at diabetes onset (n = 6) and 0.7 (0.5–1) IU at follow-up (n = 11)." (PMID 32321554, 2020). "For instance, mtDNA mutations impacting mitochondrial function and ATP production link with abnormal insulin release and β-cell development, insulin resistance, and diabetes." (PMID 32141474, 2020). "Eight participants (18%) described a hate of diabetes and wanting to regain control as their main reason for restricting insulin." (PMID 32967730, 2020). "C-P levels accurately reflect the secretion of endogenous insulin and its determination is of great significance for the classification and diagnosis of diabetes as well as the pathogenesis of diabetes." (PMID 33332396, 2020). "Elevated NEFA was acknowledged to be involved in diabetes by impairing insulin action, and despite higher NEFA concentrations in obese and diabetic individuals, there was reportedly no direct clinical evidence for beta cell lipotoxicity." (PMID 33158303, 2020). "Conditional deletion of miR-17 in mouse pancreatic β cells significantly reduced glucose tolerance and glucose-stimulated insulin secretion 55, finally promoting the development of experimental diabetes." (PMID 32802189, 2020). "Since then, an overwhelming number of published data have advocated the predictive and pathogenic relationship of increasing plasma BCAA concentration with obesity, insulin insensitivity and diabetes." (PMID 32708684, 2020). "According to the Whitehall II study, insulin sensitivity was already reduced 13 years before the onset of diabetes and the decline is steeper in the last five years before diagnosis." (PMID 32987623, 2020). "The most effective treatment for this type of diabetes is unquestionably insulin injection, essentially replacement therapy." (PMID 33167495, 2020). "Despite its shortcomings, insulin has unquestionably improved and extended a great many lives, and it continues to be a major drug of choice in many cases of diabetes." (PMID 33167495, 2020). "Finding a small molecule which can selectively activate INSR signaling in an insulin-independent manner represents a novel treatment for diabetes, including T2D." (PMID 31378829, 2020).
diabetes (continued). "Diabetes patients exhibit persistent hyperglycemia due to the impairment of beta cell insulin secretory function, insulin action or both." (PMID 33347462, 2020). "Consumption of low-glycemic foods reduces post-prandial glucose rise and insulin spikes, resulting in better diabetes control according to a recent meta-analysis." (PMID 32824428, 2020). "Decreased insulin sensitivity is an established characteristic of diabetes in individuals after pancreatitis." (PMID 32630360, 2020). "In patients with diabetes, daily supplementation with barberry extract (extracted from 10 g barberry) for 3 months reduced blood lipids, glucose, and insulin and increased TAC." (PMID 33246500, 2020). "Several studies aiming to understand how diabetes impacts the brain have employed T1D models characterized by impaired insulin secretion and chronic hyperglycemia." (PMID 33536868, 2020). "Liver is the main target organ of insulin action, and patients with diabetes‐related liver cancer show a high IR, which is characterized by the decreased sensitivity of cells and tissues to insulin, thus resulting in the decreased consumption of glucose." (PMID 33012117, 2020). "The model of streptozotocin-induced diabetes produces the partial destruction of beta cells in pancreas, therefore significantly reducing the synthesis and secretion of insulin into the circulation." (PMID 33203103, 2020). "Patient self-management is key to good diabetes outcomes, encompassing management of lifestyle, insulin dose titration, foot self-care, and adherence to treatment plans." (PMID 32508313, 2020). "Diabetes is a metabolic disorder categorized by hyperglycemia resulting from defects in insulin secretion, insulin action, or both." (PMID 33490239, 2020). "Gender, residence, marital status, exercise, duration of diabetes, insulin use, hypertension, antihypertensive drugs use, cardiovascular disease, depressive symptoms, HbA1c, SBP, DBP, and BMI differed significantly between participants with and without DPN." (PMID 33194943, 2020). "A perfect solution to diabetes would be to replenish the mass of functional pancreatic beta cells (insulin-producing cells, IPCs)." (PMID 32345350, 2020). "This is a new research avenue that will facilitate investigation to increase the understanding of the role of H2O2 in insulin resistance in skeletal muscle in diabetes and ageing." (PMID 31965006, 2020). "Diabetes mellitus (DM) is a chronic endocrine metabolic disorder characterized by hyperglycemia resulting from insulin secretion dysfunction." (PMID 33542702, 2020). "Peroxisome proliferator-activated receptor γ2 (PPARγ2) is a nuclear hormone receptor of ligand-dependent transcription factor with a key role in adipogenesis and insulin sensitization in diabetes mellitus." (PMID 33551986, 2020). "Acute insulin administration in patients with diabetes mellitus during concomitant normal blood glucose levels had a positive effect on some diastolic LV parameters in addition to the known improvement of systolic LV performance." (PMID 32308680, 2020). "This increase in the rate of older individuals with diabetes requires the management of those with physical or cognitive impairment who fail to accomplish diabetes-related self-care such as insulin injection." (PMID 33139628, 2020). "There is a general lack of studies in α-cells, and much more knowledge has been accumulated about changes in β-cell morphology, their inability of insulin secretion and even their complete destruction during the course of diabetes." (PMID 32218947, 2020). "Excess mortality in T2DM was substantially higher in people who were diagnosed with T2DM at a younger age, in those who died at a younger age, those who had a longer diabetes duration, or those who required treatment with insulin." (PMID 32962295, 2020). "Diabetes is classified into four main groups: type I (insulin dependent), type II (non-insulin dependent), gestational diabetes, and other specific types." (PMID 32190386, 2020).